CTLA4 (cytotoxic T-lymphocyte associated protein 4)
Diseases named in the same sentence as CTLA4 in open-access papers (continued):
Sharing a sentence is not in itself a finding about the gene and the disease.
tumor (continued). "When examining the tumor infiltrate, combination anti-B7x and anti-CTLA-4 treatment caused broad changes in the tumor microenvironment." (PMID 35523809, 2022). "The concept is based on blocking immune-checkpoint proteins such as programmed cell death protein 1 (PD-1), programmed death-ligand 1 (PD-L1), or cytotoxic T-lymphocyte-associated antigen 4 (CTLA-4), so that the anti-tumour T-cell response remains active." (PMID 35954496, 2022). "Neutralizing antibodies targeting PD-1 receptor of lymphocytes, its ligand PD-L1, and the cytotoxic T-lymphocyte-associated protein 4 (CTLA-4) “unleash” the tumor-specific T-cell response." (PMID 36612206, 2022). "PD-1/CTLA4 are immune cell surface marker proteins, and tumour cells cause immune evasion by altering the functions of these proteins." (PMID 35571047, 2022). "Cytotoxic T-lymphocyte Associated Protein 4 (CTLA-4) is an immune checkpoint molecule highly expressed on regulatory T-cells (Tregs) that suppresses the function of tumor-reactive T-cells responsible for eliminating cancer cells." (PMID 35326731, 2022). "An important mechanism is the expression of inhibitory ligands for CTLA-4 and PD-1 receptors on T cells and other immune cells that cause inhibition of the tumor microenvironment, known as immune checkpoints that deactivate T cells." (PMID 35775000, 2022). "By releasing immune checkpoint blockage such as cytotoxic T-lymphocyte-associated antigen 4 (CTLA4), and the programmed cell death protein 1 (PD-1) and its ligand (PD-L1), anti-tumor immune responses can be reactivated." (PMID 36499102, 2022). "Cytotoxic T lymphocyte-associated antigen (CTLA)-4 blockade has been successfully used in tumor immunotherapy." (PMID 35844804, 2022). "The expression of immune checkpoints including programmed cell death protein 1(PD-1), lymphocyte-activation gene 3 (LAG-3), cytotoxic T-lymphocyte-associated protein 4 (CTLA-4) on tumor-infiltrating CD4+ T cells was reduced as well." (PMID 35774793, 2022). "A cocktail of nivolumab, tumor excision, radiotherapy, chemotherapy, and anti-cytotoxic T lymphocyte-associated protein-4 (anti-CTLA4) is more effective than monotherapies." (PMID 35632488, 2022). "High-risk group had higher level of Treg immune cell infiltration compared with that in the low-risk group, and the tumor purity, immune checkpoint PD-1 and CTLA4, and immunity in the high-risk group were higher than those in the low-risk group." (PMID 35664744, 2022). "The targeted checkpoints are mainly the PD-L1 (programmed death-ligand 1), expressed by the tumor, and the PD-1 (programmed cell death protein 1) and CTLA-4 (cytotoxic T-lymphocyte-associated protein 4) immune cell receptors." (PMID 36140182, 2022). "OX40L and CTLA4 are present on multiple antigen-presenting cells, and their higher protein expression has been associated with reduced survival in tumor cells." (PMID 36230846, 2022). "Present attempts to restore eradication of tumor cells by the immune system mainly focus on the principle of immune checkpoint blockade, typically by blocking cytotoxic T lymphocyte-associated protein 4 (CTLA-4) or programmed cell death protein 1 (PD-1)." (PMID 35027544, 2022). "Ipilimumab is a fully humanized mAb that potentiates the anti-tumor T-cell response by blocking cytotoxic T-lymphocyte-associated antigen 4 (CTLA-4)." (PMID 35053426, 2022). "IHC staining further verified that intratumoral fibrosis was negatively associated with the expression of CTLA4 in the tumor immune microenvironment of ccRCC." (PMID 35710350, 2022). "ICIs enhance the recognition of T cells by tumor cells by targeting the inhibition of cytotoxic T lymphocyte-associated protein 4 (CTLA-4) or programmed cell death receptor 1 (PD-1)/ligand 1 (PD-L1) to alter the immune escape microenvironment of tumors." (PMID 36091070, 2022). "Literature reports some associations between CTLA-4 expression in the tumor microenvironment and worse outcomes, reaching more than 50% of cases." (PMID 36358618, 2022).
tumor (continued). "TBC1D10C also had a high positive association with tumor-infiltrating immune cells and common immune checkpoints (PD-1, CTLA-4, and TIGIT)." (PMID 35425695, 2022). "Tumor immune status analysis revealed that CTLA4 and PDCD1 (PD1) were highly expressed in the high-risk group, which responded to PD1 inhibitor therapy." (PMID 36181013, 2022). "ICIs are able to unleash anti-tumor immunity and mediate durable cancer regressions via inhibition of pathways like the cytotoxic T-lymphocyte-associated protein 4 (CTLA-4), programmed cell death-1 (PD-1), and programmed cell death ligand-1 (PD-L1)." (PMID 35345444, 2022). "To corroborate the association between tumor sialylation and T cell dysfunction, we used a mouse tumor model of genetic desialylation in combination with anti–PD-1 and anti–CTLA-4 ICB." (PMID 36322632, 2022). "The study first indicated that intratumor fibrosis was associated with CTLA4 expression in the tumor microenvironment in ccRCC." (PMID 35710350, 2022). "TNBC tumours with BRCA-1 mutations were also observed to express more PD-1 and CTLA-4 compared with BRCA-1 normal tumours." (PMID 36531051, 2022). "Although there are currently no precise biomarkers to predict the response of ICI, its efficacy, in general, is associated with the expression of (PD-1, PD-L1, and CTLA-4) and tumor mutation burden." (PMID 35327456, 2022). "In particular, high expression of CTLA4 was observed to be associated with worse outcome (P-value = 0.036), indicating a potential biomarker of R/R MM tumor prognosis." (PMID 36033464, 2022). "According to their study, a higher density of CTLA-4+ interstitial lymphocytes is associated with better OS and DFS, whereas higher CTLA-4 expression on tumor cells is associated with shorter OS." (PMID 35054356, 2022). "And a growing number of therapeutic strategies were focused on TME, such as cancer-associated fibroblasts (CAFs), tumor-associated macrophages (TAMs), and CTLA-4/PD-1/PD-L1 immune checkpoints." (PMID 36483553, 2022). "CTLA4 inhibitors predominantly cause irAE by reinitiating exhausted T effector cells in the tumor microenvironment leading to the production of autoantigens apart from neo antigens, destroying normal tissue." (PMID 35558065, 2022). "The formed PLGA-ICG-R837 nanoparticles, which trigger photothermal ablation by a near-infrared laser, can produce tumor-associated antigens in vivo, while combined with CTLA4 antibody therapy, which can prevent recurrence after tumor elimination." (PMID 36405706, 2022). "Combination with GM-CSF encoding virus vector showed enhancement in a number of tumour mature dendritic cells and macrophages in contrast to CTLA-4 virus treatment alone." (PMID 36140243, 2022). "The features suggested that HL tumor cells escaped from immunosurveillance for their survival and growth, including CTLA-4, PD-1, and LAG-3-associated immune evasion." (PMID 36035394, 2022). "Targeting of the checkpoints of immune cell activation, such as cytotoxic T lymphocyte-associated protein 4 (CTLA-4) and programmed cell death protein 1 (PD-1), have been shown to be effective means of activating anti-tumour immune responses." (PMID 35572541, 2022). "As a result, the ICI-induced blockade of the PD-1/PD-L1 and CTLA-4 axis can cause activation of T cells in tumor tissue, which then kill tumor cells by producing inflammatory factors and cytokines." (PMID 37674988, 2022). "Currently, there are three groups of American Food and Drug Administration (FDA)-approved ICIs, including cytotoxic T lymphocyte-associated protein 4 (CTLA-4), programmed cell death 1 (PD-1) on T cells, and PD-L1 on tumor cells." (PMID 35541919, 2022). "A murine mastocytoma P815 tumor model was used to analyze a therapeutic DNA vaccine encoding the P815A antigen in combination with anti-CTLA-4 and anti-PD-1 ICB therapy." (PMID 36145609, 2022).
tumor (continued). "Our results with pyridostatin provide a strong rationale for testing it in combination with immune blockade drugs (e.g. anti‐PD‐1 or anti‐CTLA4 antibodies) for the treatment of BRCA1/2‐deficient tumours." (PMID 35107878, 2022). "A greater TIDE score suggests a higher probability of tumor immune escape and lower likelihood of benefitting from anti-PD-1/CTLA4 therapy, illustrating that low-risk patients are candidates for ICB therapy." (PMID 35711437, 2022). "CDNs increased the infiltration of tumor‐specific cytotoxic T‐cells and enhanced the therapeutic efficacy of anti‐PD‐1 and anti‐CTLA‐4, reprogramming immunosuppressive, M2‐polarized tumor‐associated macrophages to a pro‐inflammatory M1‐macrophages." (PMID 35099823, 2022). "CTLA4 is limited to the activated T cells and Tregs, and CTLA4 impedes tumor progression by depleting Tregs and modulating Treg suppressive activity, and therefore, anti-CTLA4 antibodies are indicated in patients with high risk scores." (PMID 36439501, 2022). "Immune therapy currently focuses primarily on T cells (PD1/PD-L1, Cytotoxic T-lymphocyte-associated protein 4) or Tumor-associated macrophages (Colony-stimulating factor 1 receptor)." (PMID 34895349, 2021). "For other CD80/CD86-negative solid tumors, it is worthy of consideration to utilize CAR construct targeting the tumor-associated antigens as well as converting CTLA4 signals." (PMID 33868277, 2021). "CTLA4 mediated T cells inhibitory signalling has been an important phenomenon implicated in various types of infections and tumours." (PMID 33921181, 2021). "Although few studies have described the prognostic value of CTLA-4 levels in the tumor site, its expression has been associated with decreased survival in patients with nasopharyngeal carcinoma and increased survival in those with non-small-cell lung cancer." (PMID 33996698, 2021). "CD80 deactivation in these cells was associated with a “hotter” microenvironment, decreased tumor growth, and enhanced sensitivity to CTLA-4 blockade." (PMID 33923750, 2021). "Two most representative immune checkpoint pathways, cytotoxic T-lymphocyte–associated antigen 4 (CTLA-4)/B7 and PD-1/PD-L1, play critical roles in T cell coinhibition and exhaustion, by which tumors are able to evade anti-tumor immunity." (PMID 34742351, 2021). "Ipilimumab is a humanized monoclonal antibody that acts as an inhibitor of cytotoxic T-lymphocyte-associated protein 4 (CTLA-4), which in turn leads to activation of T cells resulting in tumour cell death." (PMID 32449093, 2021). "Cell surface receptors such as cytotoxic T-lymphocyte antigen-4 (CTLA-4), programmed cell death protein 1 (PD-1) or programmed cell death ligand 1 (PD-L1) are targeted by ICIs, which cause tumor cells to be destroyed by the immune system." (PMID 34203101, 2021). "Cytotoxic T lymphocyte associated protein-4 (CTLA-4) (CD152) is one of inhibitory immune checkpoints that have been identified to suppress anti-tumor immune responses in solid tumors." (PMID 33906311, 2021). "For instance, tumor cells, tumor-associated macrophages (TAMs) and stromal cells induce T cell exhaustion by activating co-inhibitory receptors such as PD-1, CTLA-4 and TIM-3." (PMID 33906694, 2021). "Tumour immunotherapy, using a combination of anti-PD1 and/or anti-CTLA4 therapy has been shown to have a survival benefit across multiple tumour types, especially when stratified to patients with high tumour mutational burden (TMB)." (PMID 33632293, 2021). "Tumor cells can evade the immune system in the TME by T-cell co-stimulation through tumor cell upregulation of immune-checkpoint co-signaling proteins such as cytotoxic T-lymphocyte-associated antigen 4 (CTLA-4) and programmed death-1 (PD-1) protein." (PMID 34877077, 2021). "In particular, Tregs express the inhibitory immune checkpoint molecule cytotoxic T-lymphocyte (associated) antigen 4 (CTLA-4), which plays a critical role in the regulation of T cell-mediated anti-tumor immunity." (PMID 34359568, 2021).
tumor (continued). "A Phase I clinical trial involving the dual blockade of VEGF (bevacizumab) and CTLA-4 (ipilimumab) revealed increased tumor antigen recognition, tumor-associated endothelial activation, and infiltration of T-cells in melanomas." (PMID 33422072, 2021). "Factors including cytotoxic T lymphocyte-associated antigen 4 (CTLA4), programmed death-1 (PD-1), and programmed death-ligand 1 (PD-L1) have been shown to play important roles in tumor treatment." (PMID 34604053, 2021). "Forkhead box P3 (FOXP3), also known as scurfin, is a transcription factor overexpressed by Tregs and associates with the up-regulation of CTLA-4 expression, which in case of iCC is predictive of tumor recurrence and chemoresistance." (PMID 33922362, 2021). "Low CTLA-4+ TILs showed a significant association with advanced tumour stage and increased number of positive LNs." (PMID 35047074, 2021). "In preclinical models, we evaluated TCR clonality in peripheral CX3CR1+ CD8+ T cells only in highly-mutated MC38 tumor-bearing mice treated with combined anti-CTLA-4/PD-L1 blockade therapy." (PMID 33658501, 2021). "The inhibition of CTLA-4 enhances T cell responses to tumor-associated neoantigens, depletes local intra-tumoral Treg cells, and shifts the balance of the tumor microenvironment away from immunosuppression." (PMID 34680601, 2021). "Hyperactivated/exhausted T cells often cause over-expression of CTLA-4 in intracellular vesicles, inhibiting immune responses against tumour cells." (PMID 34968365, 2021). "In particular, programmed cell death protein-1 (PD-1) and cytotoxic T-lymphocyte-associated protein-4 (CTLA-4), which weaken the immune function mediated by T cells, are of great importance to tumor immunosuppression." (PMID 34959285, 2021). "The tumor tissue-infiltrated CD4+ FOXP3+ Treg were also increased after CAF depletion, which reduced tumor response to gemcitabine treatment via cytotoxic T-lymphocyte-associated protein (CTLA)-4-induced immunosuppression." (PMID 34868982, 2021). "Combining IRE with anti-CTLA-4 promotes a systemic wave of functional neoantigen-specific T cells that is associated with increased primary tumor regression, deposition of tumor-specific TRM cells in multiple NLTs, and protection from tumor re-challenge." (PMID 34162858, 2021). "CTLA-4-expressing CD14+ dendritic cells (DCs) are also associated with the attenuation of anti-tumor T cell responses due to indoleamine 2, 3-dioxygenase (IDO) and IL-10 production." (PMID 34575463, 2021). "Patients with high m6A score were characterized by enhanced immune cell infiltration and prolonged survival time and were associated with lower tumor mutation burden and PD-1/CTLA4 expression." (PMID 34975871, 2021). "There is a direct association between positive VDR expression in tumor cells and positive and high CTLA4 expression in lymphocytes (P= 0.000 and 0.09 respectively)." (PMID 33906311, 2021). "Activated T cells recognize tumor antigens, but their PD-1 receptor engaged to tumor PD-L1 (programmed death-ligand 1) or their CTLA-4 (cytotoxic T-lymphocyte associated antigen 4) interaction with B7 antigen-presenting cells inhibit T cells cytotoxicity." (PMID 34359720, 2021). "Other factors such as TGF-β, IL2, IL10 and CTLA-4 are involved in tumor-associated macrophage polarization to the M2 phenotype, as well as naïve T-cell polarization into inducible T-reg." (PMID 33800796, 2021). "In 2011, the world's first immune checkpoint inhibitor, cytotoxic T lymphocyte-associated antigen 4 (CTLA-4) antibody, was approved by the U.S. Food and Drug Administration, marking a new era in tumor immunotherapy." (PMID 33854546, 2021). "In fact, CTLA-4 (cytotoxic T-lymphocyte-associated protein 4), PD-1 (programmed cell death protein 1), and its ligand PD-L1 inhibitors proved to interfere with T-cell inhibitory pathways, thereby overcoming tumor immune subversion." (PMID 34948200, 2021).
tumor (continued). "A crucial insight into this endeavor is that engagement of immune checkpoint molecules (i.e., programmed cell death protein 1 (PD-1) and cytotoxic T-lymphocyte-associated antigen 4 (CTLA4)) is a key mechanism facilitating tumor anti-pathogenicity." (PMID 34158025, 2021). "Checkpoint inhibitors increase endogenous anti-tumor activity by blocking components of the immune system, including cytotoxic T lymphocyte-associated antigen 4 (CTLA-4), programmed cell death protein-1 (PD-1), or ligand 1 (PD-L1)." (PMID 34960142, 2021). "Nevertheless, the dual-blockade of CD39 and CD73, in combination with αPD-1/αCytotoxic T lymphocyte-associated protein-4 (CTLA-4) was successful in promoting robust anti-tumour T cell immunity in known therapy-resistant cancer models." (PMID 33401460, 2021). "In contrast to this, capecitabine was found to inhibit the expression of CTLA-4 in colorectal cancer cells, and the anti-tumor activity of orlistat, an FASN inhibitor, has been associated with the reduction of PD-L1 expression." (PMID 34639014, 2021). "Genetic variations affecting expression of CTLA4 are known to influence the immune response, resulting in a higher risk for autoimmune and neoplastic diseases." (PMID 33802937, 2021). "Further, the acidic TME impairs the secretion of proinflammatory cytokines by T-cells (e.g., IL-2, TNFs and IFN-γ) and upregulates CTLA-4 expression, rendering tumour infiltrating T-cells more susceptible to negative regulatory signals." (PMID 33923305, 2021). "To further explore tumor environment, we compared the expression levels of PD-1, PD-L1, PD-L2, and CTLA-4 between high and low risk groups." (PMID 34854360, 2021). "Programmed death ligand 1 (PD-L1) and cytotoxic T lymphocyte-associated antigen-4 (CTLA-4) are immune checkpoints that induce tumour immune escape." (PMID 35047074, 2021). "Correlation analyses were performed to assess relationships among risk score, tumor mutational burden, and expression of the three immune checkpoint genes PD-1, PD-L1, and CTLA-4." (PMID 34925311, 2021). "Our study found that the number of tumor stem cells in the high-risk group was significantly higher than that in the low-risk group, and CTLA-4 was highly correlated with tumor stem cells." (PMID 34553071, 2021). "Currently, about 20 combination clinical trials with an anti-PD1/L1 are ongoing in localized and advanced stages, in association with radiotherapy, chemotherapy, tumor vaccines, anti-CTLA4, anti-EGFR, or antiangiogenic molecules." (PMID 34359795, 2021). "Other groups confirmed that the microbiota affects tumor response to CPIs, since the enrichment of Faecalibacterium and other Firmicutes was associated with beneficial clinical response to anti-CTLA-4." (PMID 34072037, 2021). "T cells, which were thought to be primarily affected by ICB with anti-PD1 and anti-cytotoxic T-lymphocyte-associated antigen 4 (CTLA4) antibodies, can promote abnormal tumor vessel normalization." (PMID 34476218, 2021). "Recently, in vitro study showed that anti-PD1 and anti-CTLA4 caused prominent tumor reduction in allograft TSC tumors." (PMID 34243823, 2021). "Preclinical murine models of BRCA deficient OC revealed a strong anti-tumour immune response to PARPi combined with anti-PD-1 or anti-CTLA-4 therapy." (PMID 34944851, 2021). "High levels of butyrate and proprionate have been reported to interfere with the anti-tumor activity of CTLA-4 blockade in cancer patients and associates to higher frequencies of blood Tregs." (PMID 33802979, 2021). "Recent advances in ICB therapy, such as targeting programmed cell death protein 1 (PD-1)/PD-ligand 1 (PD-L1) and/or cytotoxic T-lymphocyte-associated protein 4 (CTLA-4), illustrate powerful enhancement of the patient’s anti-tumor immune responses." (PMID 34758832, 2021).